SLC6A3 (solute carrier family 6 member 3)
Diseases named in the same sentence as SLC6A3 in open-access papers (continued):
Sharing a sentence is not in itself a finding about the gene and the disease.
schizophrenia (108 papers, 2006 to 2026). A major psychotic disorder characterized by abnormalities in the perception or expression of reality. "In haloperidol-treated schizophrenia patients carrying the SLC6A3 3′UTR VNTR alleles with 9 or 10 repeats, only nominally significant findings of the higher scores at ESRS subscales VI and VIII in the carriers of 9 repeats (9R) allele were determined." (PMID 36551993, 2022). "Controversial information was obtained by studying the effect of polymorphism in SLC6A3 on pharmacogenetics of adverse events in schizophrenia treatment." (PMID 30967134, 2019). "Studies have also implicated SLC6A3, coding for the dopamine transporter, in schizophrenia phenotypes and response to medication." (PMID 30687136, 2018). "The less-studied COMT rs174696 and SLC6A3 (DAT1) rs464049 appear to interactively influence the risk of schizophrenia, but their functionality is yet unknown." (PMID 39595853, 2024). "In contrast to our earlier results, in the present study we have determined only nominally higher scores at ESRS subscales VI and VIII for AIP in the haloperidol-treated schizophrenia patients carrying the 9 repeats (9R) allele of SLC6A3 3′UTR VNTR polymorphism." (PMID 36551993, 2022). "SLC6A3 variants rs2550956 and rs6347 were associated with schizophrenia." (PMID 25025909, 2014). "Slc6a3−/− mice have been proposed as a model for schizophrenia and the DA hypothesis of schizophrenia states that DA elevation is causal to the behavioral symptoms of this psychiatric condition." (PMID 25546305, 2014). "Besides, SLC6A3 polymorphisms are associated with schizophrenia." (PMID 25522158, 2014). "RBFOX3/NEUNlow DA neurons had increased expression of ectonucleoside triphosphate diphosphohydrolase 1 antisense RNA 1 (ENTPD1-AS1) and dopamine transporter 1 (SLC6A3/DAT1) in schizophrenia cases." (PMID 39397771, 2025). "The dysregulation of COMT expression has been demonstrated in the pathophysiology of schizophrenia Dopamine transporter (DAT) is encoded by the Solute Carrier Family 6 Member 3 (SLC6A3) gene and is located on the neuronal cell membrane." (PMID 38203806, 2024). "Psychotic disturbances have been linked to the aberrant release of dopamine and neurotransmission, which possibly implicates SLC6A3 in schizophrenia." (PMID 36980961, 2023). "Gene-associated studies have shown a possible relationship between variants of genes related to dopamine signallings, such as catechol O-methyltransferase (COMT), monoamine oxidase (MAO), and dopamine transporter (SLC6A3), and the risk of schizophrenia." (PMID 36979236, 2023). "Mutations or polymorphisms in the DAT gene SLC6A3 contribute to ADHD, OCD, bipolar disorder and schizophrenia." (PMID 35246636, 2022). "Both HTR2C polymorphisms were successfully determined in 229 schizophrenia patients, whereas 219 patients were successfully genotyped for HTR6 polymorphism and 216 patients for SLC6A3 polymorphism." (PMID 36551993, 2022). "In the present study we investigated the possible association of polymorphisms from five candidate genes RGS4, SLC6A3, PIP4K2A, BDNF, PI4KA with response to antipsychotic in variably ill schizophrenia patients." (PMID 25025909, 2014). "Single locus analysis showed significant association of nine variants from SLC6A3, PIP4K2A and BDNF genes with incomplete antipsychotic response in schizophrenia patients with high severity." (PMID 25025909, 2014). "As some of the individual differences in the susceptibility to AIP might be due to the genetic background, this study aimed to examine the associations of SLC6A3, HTR2C and HTR6 gene polymorphisms with AIP in haloperidol-treated schizophrenia patients." (PMID 36551993, 2022). "Therefore, the haloperidol-treated schizophrenia patients were grouped according to the combined presence of HTR6 T and SLC6A3 9R alleles, which were identified as risk alleles for AIP." (PMID 36551993, 2022).
schizophrenia (continued). "Interestingly, this study used Slc6a3-/- mice to model a hyper-dopaminergic phenotype, due to their deletion of DA transporter (DAT) for DA re-uptake, a potential model for schizophrenia." (PMID 32655359, 2020). "The dopamine transporter gene (SLC6A3) appears to be one of the most important candidate genes for affecting mental disorders, as it is the target of many psychostimulants that cause symptoms similar to the positive symptoms of schizophrenia." (PMID 30967134, 2019). "With this background, in the present study, we investigated 53 polymorphisms from five genes (RGS4, SLC6A3, PIP4K2A, BDNF and PI4KA) in 423 south Indian schizophrenia cases segregated into low and high severity of illness to assess their influence on antipsychotic response." (PMID 25025909, 2014). "Regarding the association with schizophrenia, two studies have demonstrated that rs3756450 was not the top-hit polymorphism of SLC6A3; however, it showed a highly significant signal in an association analysis between patients with schizophrenia and healthy subjects." (PMID 38476817, 2023). "Moreover, gene-associated studies showed a possible relationship between the risk of schizophrenia and some variants in genes related to dopamine signaling, i.e., catechol-O-methyltransferase (COMT), monoamine oxidase (MAO), dopamine transporter (SLC6A3), and dystrobrevin-binding protein 1 (DTNBP1)." (PMID 37899392, 2023). "Therefore, further studies should be conducted to test a wider range of antipsychotics and other drugs for the association of the SLC6A3, HTR2C and HTR6 polymorphisms, as well as CYP2D6 gene variants with AIP, in both male and female schizophrenia patients of different ethnicities." (PMID 36551993, 2022).
Anxiety (92 papers, 2009 to 2026). Intense feelings of nervousness, tension, or panic often arise in response to interpersonal stresses. "Our results showed that rs2652511 (SLC6A3 locus) was an independent risk factor for the anxiety symptom in children with ADHD, which is new information on SLC6A3 gene research." (PMID 36213906, 2022). "However, the IL-12b gene mutation was significantly associated with anxiety (P = 0.031), and the SLC6A3 gene mutation was significantly associated with low QOL (P = 0.017)." (PMID 36405903, 2022). "COMT, SLC6A4, SLC6A3, and IL-12b gene mutations were also associated with melanoma sites and TNM stage, anxiety, and QOL." (PMID 36405903, 2022). "Although SLC6A3 (DAT1) and COMT genes were significant for the risk of suicidal attempts, they showed a lack of association with the severity of the symptoms of depression, situational anxiety, and personal anxiety." (PMID 34199792, 2021).
Cognitive impairment (73 papers, 2012 to 2026). Abnormal cognition is characterized by deficits in thinking, reasoning, or remembering. "Other studies found that DβH was associated with cognitive impairment (Alzheimer's disease), working memory, and severity of psychotic symptoms, and SLC6A3 with response inhibition." (PMID 26308205, 2015).
dementia (55 papers, 2012 to 2026). Loss of intellectual abilities interfering with an individual's social and occupational functions. "Slc6a3 encoded the dopamine transporter and its variant carriers reduced cognitive performance and were at greater risk of developing dementia." (PMID 36352898, 2022).
attention deficit-hyperactivity disorder (53 papers, 2005 to 2026). A disorder characterized by a marked pattern of inattention and/or hyperactivity-impulsivity that is inconsistent with developmental level and clearly interferes with functioning in at least two settings (e.g. at home and at school). "Additionally, variants in DRD5 and SLC6A3 have been associated with attention deficit hyperactivity disorder (ADHD)." (PMID 32824878, 2020). "The dopamine transporter gene, DAT1 (SLC6A3), has been studied extensively as a candidate gene for attention-deficit/hyperactivity disorder (ADHD)." (PMID 26935821, 2016). "The dopamine transporter SLC6A3 (solute carrier family 6 member 3, also termed DAT1) regulates dopamine concentrations in the brain and expression changes are associated with Parkinson’s syndrome and attention-deficit/hyperactivity disorder." (PMID 26831905, 2016).
bipolar disorder (40 papers, 2009 to 2025). A disorder of the brain that causes unusual shifts in mood, energy, activity levels and the ability to carry out day-to-day tasks. "The identification of these individuals adds to reports of heterozygous carriers of coding variants in SLC6A3 associated with neuropsychiatric diseases, including bipolar disorder, ADHD, and autism spectrum disorder." (PMID 37443770, 2023). "The Ala559Val (A559V) mutation of Slc6a3 is found not only in ASD but also in ADHD and bipolar affective disorder." (PMID 37238676, 2023). "One of the detected genetic polymorphisms in SLC6A3 was associated with pediatric bipolar disorder; although no connection was found between bipolar disorder in adults and postoperative delirium." (PMID 26106326, 2015). "In addition, SLC6A3 variants are associated with neuropsychiatric diagnoses, including autism spectrum disorder (ASD), attention deficit hyperactivity disorder (ADHD), and bipolar disorder." (PMID 37443770, 2023). "Subsequently, genetic polymorphisms within the single copy gene coding for the DAT (DAT1, SLC6A3) were investigated in relation to cocaine dependence and abuse, methamphetamine psychosis, attention-deficit/hyperactivity disorder (ADHD) and treatment, and bipolar disorder." (PMID 31708815, 2019).
Obesity (36 papers, 2009 to 2025). Accumulation of substantial excess body fat. "We report a protective effect of the 9 allele of the SLC6A3 VNTR on overweight and obesity and a novel association between the presence of the G allele of SLC6A3 Ex9-55A>G polymorphism and being underweight." (PMID 19183461, 2009). "The results revealed that 18 of the DMR genes were associated with addiction and obesity (ADCY3; ADCY9; ATF4; CDK5R1; CHRNB2; GABRD; GABRG3; GNB1; GNB3; GRK5; HDAC4; HDAC9; MAP2K1; PDE11A; PDE2A; PDE3A; PPP1CA; SLC6A3)." (PMID 34389046, 2021). "This present study supports the association between the presence of the 9 allele of SLC6A3 VNTR and decreased risk of obesity." (PMID 19183461, 2009). "Previously, it was reported that Slc6a3 was hypermethylated in the promoter region in response to high-fat-sucrose diet and downregulated in the nervous system of prenatally stressed female rats and murine models of diet-induced obesity." (PMID 32599859, 2020). "In addition, methylation aberrations at SLC6A3 gene were related to triglyceride level and obesity in humans." (PMID 32599859, 2020). "Among individuals with the DRD2/ANKK1 haplotype (T-C-T-A) previously associated with obesity, no marked increase in effect of the SLC6A3 VNTR on obesity was observed (** = reference; OR*9 = 0.89, 95% CI 0.54–1.46; OR99 = 0.54, 95% CI 0.23–1.33, p-value for interaction = 0.62)." (PMID 19183461, 2009).
dementia with Lewy bodies (29 papers, 2014 to 2026). "Canonical correlation analysis (CCA) was used to integrate 25,003 nuclei from human control and diseased (PD and Lewy body disease) donors with our lesioned and intact nuclei from the Th+/ Slc6a3+dataset." (PMID 38587883, 2024).
Dystonia (29 papers, 2013 to 2025). An abnormally increased muscular tone that causes fixed abnormal postures. "DTDS is a primary neurotransmitter disorder that presents with infantile parkinsonism-dystonia due to biallelic loss-of-function mutations in the SLC6A3 gene (OMIM # 613135)." (PMID 37443770, 2023). "Mutations in the human dopamine (DA) transporter (hDAT) gene (SLC6A3) have been linked to a distinct type of infantile parkinsonism-dystonia, referred to as DA transporter deficiency syndrome (DTDS)." (PMID 34002696, 2021). "Dopamine transporter deficiency syndrome is an SLC6A3-related progressive infantile-onset parkinsonism-dystonia that mimics cerebral palsy." (PMID 24613933, 2014). "Infantile parkinsonism-dystonia due to dopamine transporter deficiency syndrome (DTDS) is an ultrarare childhood movement disorder caused by biallelic loss-of-function mutations in the SLC6A3 gene." (PMID 37443770, 2023). "Dopamine transporter deficiency syndrome due to SLC6A3 mutations is the first inherited dopamine ‘transportopathy’ to be described, with a classical presentation of early infantile-onset progressive parkinsonism dystonia." (PMID 24613933, 2014). "Indeed, loss-of-function mutations in SLC6A3 have recently been linked to a complex movement disorder involving infantile Parkinsonism and dystonia." (PMID 25253562, 2014). "Chorea was also a prominent HMD in seven children with neurotransmitter defects (DDC, TH, SLC6A3), commonly in tandem with dystonia (n = 5), ballismus (n = 2), myoclonus (n = 1), coarse tremor (n = 3), and stereotypies (n = 1)." (PMID 36054588, 2022).
synucleinopathy (28 papers, 2014 to 2026). A neurodegenerative disease that is characterized by the abnormal accumulation of aggregates of alpha-synuclein protein in neurons, nerve fibers or glial cells. "Our RNAseq analysis identified decreased transcription of the monoamine transporters Slc18a2 (VMAT2) and Slc6a3 (DAT), in early synucleinopathy." (PMID 38172128, 2024). "Finally, transcripts known to be involved in Tau- and synucleinopathies include IGLON5, CAV1, GFRA2, SYNGR3, and SLC6A3, with the latter being particularly interesting as its genetic variants lead to Parkinsonism-dystonia infantile (PKDYS) syndrome." (PMID 35883433, 2022).
Dyskinesia (20 papers, 2011 to 2025). A movement disorder which consists of effects including diminished voluntary movements and the presence of involuntary movements. "SLC6A3 SNPs have shown associations with dyskinesia, VHs, and motor response to acute levodopa challenge." (PMID 30745869, 2019).
alcoholism (18 papers, 2008 to 2023). "Genotype distributions and allelic frequencies of the polymorphisms in the SLC6A3 (DAT) gene between patients with alcohol dependence and controls in a Han Chinese population." (PMID 28182634, 2017). "Multivariate logistic regression analyses of the sixteen polymorphisms of SLC6A3 (DAT) gene as risk factors for alcohol dependence (AD) and its subgroups in a Han Chinese population." (PMID 28182634, 2017). "Haplotype analysis of SLC6A3 (DAT) gene in patients with alcohol dependence (N = 637) and controls (N = 523)." (PMID 28182634, 2017). "We now report the results of the analysis of the relationship between ADHD, alcoholism and DAT1/SLC6A3 gene polymorphism in a subset of a population sample numbering a total of 1312 persons." (PMID 26058807, 2015).
cocaine addiction (17 papers, 2011 to 2025). "Significantly, a genetic variation in the SLC6A3 gene (encoding DAT) has been associated with disulfiram treatment for cocaine addiction, with patients with higher DAT levels having better treatment outcomes than those with lower DAT levels." (PMID 34635637, 2021). "Our findings provide preliminary evidence of the association between the ABCB1 polymorphism and heroin or cocaine dependence and the association between SLC6A3 and heroin or cocaine dependence was confirmed." (PMID 24892317, 2013).
autism spectrum disorder (11 papers, 2015 to 2025). A spectrum of developmental disorders that includes autism, and Asperger syndrome. "Our laboratory recently characterized a novel autism spectrum disorder (ASD)-associated de novo missense mutation in the human dopamine transporter (hDAT) gene SLC6A3 (hDAT T356M)." (PMID 25741436, 2015). "Notably, Slc6a3, a gene encoding a sodium-dependent dopamine transporter and associated with anxiety disorder in autism spectrum disorder, is upregulated (by 4 fold) in the neocortex of TDP-43 cKO mice but only at the age of 3 months." (PMID 30922385, 2019).
nicotine dependence (11 papers, 2010 to 2024). Physical and psychological dependence on nicotine. "However, a study on a Chinese population found that a higher SLC6A3 score was associated with the possibility of quitting smoking among those with a lower level of nicotine dependence." (PMID 33287325, 2020). "The genotyping results suggest that nicotine dependence in current smokers who are homozygous for the SLC6A3 10r allele was lower than that in individuals carrying the minor alleles, and that CYP2A6 polymorphisms might mediate this association." (PMID 25526961, 2014). "Genotyping results suggested that nicotine dependence among current smokers homozygous for the SLC6A3 10r allele was lower than that of smokers carrying the minor alleles, and that the CYP2A6 polymorphism might mediate this association." (PMID 25526961, 2014). "Our findings suggested that the age of smoking initiation might be associated with nicotine dependence, under the influence of the SLC6A3 VNTR polymorphism." (PMID 25526961, 2014). "The 10r allele has been implicated in reduced SLC6A3 protein expression; thus, it might decrease the extent of nicotine dependence, by increasing the total amount of dopamine that is released into the synaptic cleft, thereby providing a greater reward from the dopaminergic effects of nicotine." (PMID 25526961, 2014). "The present study also examined the effect of smoking history (age at which the participant began smoking and duration of smoking) on the association between SLC6A3, ANKK1/DRD2, and CYP2A6 polymorphisms and nicotine dependence." (PMID 25526961, 2014). "This study provides preliminary results regarding the effect of the SLC6A3 VNTR, ANKK1/DRD2 TaqIA, and CYP2A6*4 polymorphisms on smoking cessation and nicotine dependence in a Japanese population." (PMID 25526961, 2014). "It was recently demonstrated that the number of tandem repeats and methylation levels of the first intron of SLC6A3 gene might be related to nicotine dependence and a potentially increased tendency to start smoking and an impaired ability to quit." (PMID 35203939, 2022). "This study examined whether functional polymorphisms in SLC6A3, ANKK1/DRD2, and CYP2A6 affect smoking cessation and nicotine dependence in a Japanese population." (PMID 25526961, 2014). "Our results suggested that the age at which current smokers began smoking might moderate the effect of SLC6A3 and CYP2A6 polymorphisms on nicotine dependence." (PMID 25526961, 2014). "Finally, the relationship between the IRS group endophenotype and other genetic polymorphisms related to the brain’s reward system and nicotine dependence should be examined, including dopamine D4 receptor (DRD4) and DA transporter (SLC6A3) genes." (PMID 24065931, 2013). "We found that current smokers with the 10r/10r genotype were more likely to have low nicotine dependence based on HSI analysis, although the genotypic differences between current and former smokers were not significant for any of the SLC6A3, ANKK1/DRD2, and CYP2A6 polymorphisms." (PMID 25526961, 2014). "We found that current smokers with the SLC6A3 10r/10r genotype were more likely to have low nicotine dependence, based on HSI analysis, although the genotypic differences between current and former smokers were not significant for any of the SLC6A3, ANKK1/DRD2, and CYP2A6 polymorphisms tested." (PMID 25526961, 2014).
mental disorder (9 papers, 2013 to 2025). A disease that has its basis in the disruption of mental process. "However, current research on SLC6A3 predominantly relates to mental disorders, while studies on OPRM1 primarily focus on pain management." (PMID 40910010, 2025).
dependence (8 papers, 2014 to 2025). "Nonetheless, twelve genes contained three or more DM loci, including several genes previously involved in studies of alcohol exposure and dependence, but not present in the Phenocarta list, such as SLC6A3 and DRD4." (PMID 27358653, 2016).